ALK (ALK receptor tyrosine kinase)
Diseases named in the same sentence as ALK in open-access papers (continued):
Sharing a sentence is not in itself a finding about the gene and the disease.
non-small cell lung carcinoma (continued). "For non-small cell lung cancer (NSCLC), numerous clinical trials have demonstrated intracranial activity for inhibitors of EGFR and ALK." (PMID 31803366, 2019). "STAT3 suppression decreases PD-L1 expression in ALK-positive anaplastic large cell lymphoma (ALCL) and KRAS-mutant non-small cell lung cancer (NSCLC) cells." (PMID 31835799, 2019). "We examined the impact of the sequential treatment of targeted therapy and chemotherapy among advanced anaplastic lymphoma kinase (ALK), non-small cell lung cancer (NSCLC) patients." (PMID 30699985, 2019). "Brain metastases (BM) are common in non-small cell lung cancer patients including in molecularly selected populations, such as EGFR-mutant and ALK-rearranged tumors." (PMID 29696132, 2018). "The interpretation of FISH signals followed the same criteria used for ALK and ROS1 rearrangements in non small cell lung cancers." (PMID 29515761, 2018). "The most extensively studied ALK inhibitor in neuroblastoma, crizotinib, is a small molecule competitive inhibitor of ALK and MET kinase activity and is FDA approved for use in adult patients with ALK-translocated non-small cell lung cancer (NSCLC)." (PMID 30326621, 2018). "Crizotinib, an anaplastic lymphoma kinase (ALK) inhibitor, is FDA-approved for the treatment of non-small cell lung carcinoma (NSCLC)." (PMID 29876021, 2018). "Many patients with brain metastases from non-small cell lung cancer have limited survival, while others survive for several years, depending on patterns of spread, EGFR and ALK alterations, among others." (PMID 28651600, 2017). "For example, a fraction of non-small cell lung carcinoma (NSCLC), inflammatory myofibroblastic tumor, and anaplastic large cell lymphoma, which share ALK fusions, can be treated with ALK inhibitors and this strategy has shown clinical efficacy." (PMID 28489584, 2017). "Here we consider polypharmacological targeting of protein kinases ALK, MET, and EGFR (and its drug resistant mutant T790M) in non small cell lung cancer as an example." (PMID 29086093, 2017). "One common mechanism of ALK activation in tumors is ALK gene rearrangement leading to fusion protein like NPM-ALK in anaplastic large cell lymphomas and EML4–ALK in non-small-cell lung cancer." (PMID 28359267, 2017). "The authors analyzed 34 ALK-positive and 33 ALK-negative FFPE non-small cell lung cancer samples, obtaining 93% concordance with FISH and 98% concordance with immunohistochemistry." (PMID 28549458, 2017). "Intracranial effect of tyrosine kinase inhibitors ALK inhibitors and epidermal growth factor receptor (EGFR) inhibitors in trials in non-small cell lung cancer (NSCLC)." (PMID 28424757, 2017). "c-MET is considered a promising oncogenic driver in non-small cell lung cancer (NSCLC) after the discovery of epidermal growth factor receptor (EGFR) and anaplastic lymphoma kinase (ALK)." (PMID 28442019, 2017). "Anaplastic lymphoma kinase (ALK) rearrangements, found in approximately 5 % of non-small cell lung cancers (NSCLCs), are relatively rare genetic alterations compared with epidermal growth factor receptor (EGFR) or KRAS mutations." (PMID 27756333, 2016). "Further studies have revealed numerous different ALK fusion proteins in other tumors such as inflammatory myofibroblastic tumor (IMT), diffuse large B cell lymphoma (DLBCL) and non-small cell lung cancer (NSCLC) among others." (PMID 27049722, 2016). "It has been proven that epidermal growth factor receptor (EGFR), anaplastic lymphoma kinase (ALK), and KRAS are common driver genes in non-small cell lung cancer (NSCLC)." (PMID 27760592, 2016). "Epidermal growth factor receptor (EGFR), and anaplastic lymphoma kinase (ALK), are important oncogenic drivers in non-small-cell lung cancer (NSCLC), and other oncogenic drivers in NSCLC, such as ROS1 and KRAS, have also been found." (PMID 27533086, 2016).
non-small cell lung carcinoma (continued). "The correlation between ALK gene copy number gain (ALK-CNG) and prognosis in the context of advanced non-small-cell lung cancer (NSCLC) remains a controversial issue." (PMID 27561692, 2016). "Aberrant activation of anaplastic lymphoma kinase (ALK) has been described in a range of human cancers, including non-small cell lung cancer and neuroblastoma." (PMID 26418745, 2015). "Non-small cell Lung cancer is now a heterogenous disease with EGFR, BRAF, Her2/Neu aberrations or ALK, ROS1, RET or FGFR fusions." (PMID 26510912, 2015). "We confirmed the expressions of ALK, MET, and ROS1 mRNA (receptor tyrosine kinases that serve as therapeutic targets in non-small-cell lung cancers), in the mouse retina." (PMID 26271036, 2015). "Crizotinib, a potent and specific small molecule inhibitor of both ALK and c-MET tyrosine kinases, was approved by the Food and Drug Administration (FDA) for the treatment of non-small-cell lung cancer (NSCLC) patients with ALK gene rearrangement (ALK+)." (PMID 24422905, 2014). "The most advanced molecule crizotinib, which targets the receptor tyrosine kinases ALK and c-MET, has been approved by the US Food and Drug Administration for the treatment of patients with ELM4-ALK positive non-small-cell lung carcinoma." (PMID 23646137, 2013). "An ALK inhibitor, crizotinib, has been recently FDA approved as a therapy for late stage non-small cell lung cancer with little side effects." (PMID 24163262, 2013). "Additionally, entrectinib inhibits ROS1 and ALK, making it beneficial for metastatic, ROS1-positive non-small-cell lung cancer (NSCLC)." (PMID 40141188, 2025). "ALK rearrangements occur in about 5% of non-small cell lung cancer (NSCLC) cases, especially in younger, light, or non-smokers, and are commonly found in adenocarcinomas." (PMID 41378298, 2025). "In non-small cell lung cancer (NSCLC), ALK fusion proteins, exemplified by EML4-ALK, promote tumor cell proliferation, survival, and migration through persistent activation of downstream oncogenic signaling pathways, representing a key molecular subtype and a primary target for precision therapy." (PMID 41614760, 2025). "Indeed, the resistance of non-small cell lung cancer (NSCLC) to several RTK inhibitors, including those targeting EGFR-, ALK-, and MET-signaling, has been shown to result from EMT." (PMID 40943068, 2025). "Non-small cell lung cancer (NSCLC) often harbors oncogenic driver alterations such as epidermal growth factor receptor (EGFR), anaplastic lymphoma kinase (ALK), or Kirsten rat sarcoma viral oncogene homolog (KRAS), which can be effectively targeted with tyrosine kinase inhibitors (TKIs)." (PMID 40723270, 2025). "In the case of ALK-positive, 2-year treatment with alectinib has been shown to clearly improve DFS compared to standard adjuvant chemotherapy in patients with stage IB (≥4 cm)–IIIA non-small cell lung cancer resection." (PMID 40650316, 2025). "Monotherapy ICIs represent groundbreaking front-line treatment options for EGFR/ALK/ROS1 non-mutant non-small cell lung cancer (NSCLC) with high PDL1 expression (≥50% expression)." (PMID 40422518, 2025). "Among the various oncogenic drivers in patients with non-small cell lung cancer (NSCLC), rearrangements in the anaplastic lymphoma kinase (ALK) gene are considered to be potent drivers, presented in approximately 5% of cases, second only to epidermal growth factor receptor (EGFR) mutations." (PMID 40606995, 2025). "Likewise, the evaluation of genes such as ALK, ROS1, RET, and HER2 is crucial in assessing non-small-cell lung cancer (NSCLC), as established in the National Comprehensive Cancer Network (NCCN) guidelines." (PMID 39338229, 2024). "It is approved for the treatment of various cancers, including epidermal growth factor receptor (EGFR) negative, anaplastic lymphoma kinase (ALK) rearrangement negative non-small cell lung cancer (NSCLC)." (PMID 39512511, 2024).
non-small cell lung carcinoma (continued). "Given advancements in adjuvant treatments for non-small-cell lung cancer (NSCLC) with epidermal growth factor receptor (EGFR) and anaplastic lymphoma kinase (ALK)-targeted therapies, it is important to consider postoperative targeted therapies for other early-stage oncogene-addicted NSCLC." (PMID 39734710, 2024). "Our in vitro characterization data indicate that VH20 could be a promising ALK-targeting sdAb with potential applications in ALK-expressing tumors, including neuroblastoma (NBL) and non-small cell lung cancer." (PMID 38804307, 2024). "The main druggable genetic alterations in non-small cell lung cancer involved EGFR (epidermal growth factor receptor), KRAS (Kirsten rat sarcoma viral oncogene homolog), ALK (anaplastic lymphoma kinase), BRAF (V-raf murine sarcoma oncogene homolog B1), and ROS1 (c-ros oncogene 1) genes." (PMID 39199653, 2024). "The study population consisted of ALK-positive Non-Small Cell Lung Cancer (NSCLC) patients who had not received prior treatment with an ALK inhibitor." (PMID 39707229, 2024). "It was 1.2% among 255 adenocarcinoma and 246 non-small cell carcinomas without EGFR/ALK aberrations." (PMID 37374289, 2023). "ALK inhibition is a known mechanism for inducing apoptosis, and cancer cells (such as non-small-cell lung cancers (NSCLCs) and RMS) are often dependent on ALK and ROS1 function, providing a reasonable rationale for evaluating crizotinib and ceritinib in these cancers." (PMID 37958442, 2023). "Anaplastic lymphoma kinase (ALK)-targeted therapies, such as crizotinib, ceritinib, brigatinib, loratinib, and alectinib, are well-established FDA-approved treatment options in ALK-translocated non-small cell lung cancer (NSCLC)." (PMID 37434642, 2023). "Crizotinib is approved for ALK and ROS1 gene rearrangement in non-small-cell lung cancer (NSCLC)." (PMID 37046637, 2023). "More clinical evidence is needed regarding the relative priority of treatments for brain metastases (BMs) from EGFR/ALK-negative/unselected non-small cell lung cancer (NSCLC)." (PMID 36820064, 2023). "Dysgeusia is also a common toxicity reported with crizotinib, a multitargeted TKI of anaplastic lymphoma kinase (ALK), mesenchymal-to-epithelial transition (MET) protein, and ROS proto-oncogene 1 (ROS1) used for the treatment of ALK-positive non-small cell lung cancer (NSCLC)." (PMID 37175898, 2023). "Depending on the type of cancer, certain biomarker tests are needed in order to decide on a treatment strategy (e.g., RAS/BRAF testing for colorectal cancer; an HER2 testing for gastric cancer; and EGFR, ALK, ROS1, and PD-L1 expression testing for non-small-cell lung cancer)." (PMID 37599324, 2023). "The patient is a 19-year-old non-smoker with Stage IV ALK-rearranged non-small cell lung cancer, who presented with right neck and chest pain and Horner’s syndrome." (PMID 36713501, 2022). "Evidence from preclinical and clinical trials suggests MET activation serves as a primary oncogenic driver in a subset of patients with non-small cell lung cancer (NSCLC) and as a secondary driver of acquired resistance to targeted therapy in EGFR-mutant or ALK-positive patients." (PMID 35626038, 2022). "First-line treatment of patients with metastatic non-squamous, non-small cell lung cancer (Nsq NSCLC) with no EGFR or ALK genomic tumor aberrations." (PMID 35037899, 2022). "This research shows that pembrolizumab monotherapy can be extended as a first-line therapy to patients with locally advanced or metastatic non-small cell lung cancer without sensitizing EGFR or ALK alterations and with low PD-L1 TPS." (PMID 35159131, 2022). "The patient was a 47-year-old female with EGFR exon 19-21 wild type, ALK negative non-small cell lung cancer (NSCLC)." (PMID 36341335, 2022).
non-small cell lung carcinoma (continued). "The treatment of non-small cell lung cancer (NSCLC) has recently evolved with the introduction of targeted therapy based on the use of tyrosine kinase inhibitors (TKIs) in patients with certain gene alterations, including EGFR, ALK, ROS1, BRAF, and MET genes." (PMID 36139444, 2022). "Inhibition of anaplastic lymphoma kinase (ALK) by six approved molecules, i.e., Alectinib, Brigatinib, Ceritinib, Crizotinib, Entrectinib, and Lorlatinib, has been employed for the treatment of NSCLC (Non-Small Cell Lung Cancer) (link)." (PMID 37305347, 2022). "NGS has the potential to improve the detection of ALK and ROS1 rearrangements in cytological samples, and may become the gold standard for molecular genotyping of patients with advanced non-small cell lung cancer." (PMID 36142468, 2022). "The US FDA has approved pembrolizumab as a single-agent first-line treatment for patients with stage III or metastatic non-small-cell lung cancer who have PD-L1 expression ≥1% and no EGFR or ALK mutations." (PMID 36411824, 2022). "ALK-EML4 fusions have been reported in 2–7% of patients with advanced non-small-cell lung cancer (NSCLC), and clinical trials are ongoing to determine if ALK inhibitors are currently approved for use in NSCLC can effectively target these fusions and overcome resistance." (PMID 35326655, 2022). "In January 2021, tiragolumab (anti-TIGIT) combined with atezolizumab was approved by FDA for the treatment of metastatic non-small cell lung cancer patients with PD-L1 but without EGFR/ALK genome abnormalities." (PMID 35875070, 2022). "First-line treatment for patients with metastatic non-small cell lung cancer whose tumors express PD-L1(≥1%) with no epidermal growth factor receptor (EGFR) or anaplastic lymphoma kinase (ALK) genomic tumor aberrations." (PMID 35037899, 2022). "Materials and Methods: Using a nationwide real-world database, we included adults with advanced non-small cell lung cancer (aNSCLC, stage IIIB- IV) diagnosed January 2015 – May 2019, with documented ALK testing results and smoking status." (PMID 34786182, 2021). "Here we investigated the therapeutic potential of crizotinib, a TKI approved for targeting ALK and ROS1 in non-small cell lung cancer patients, which inhibited also the ABL1 kinase in cell-free systems, for the treatment of advanced and therapy-resistant Ph+ leukemia." (PMID 34110462, 2021). "Furthermore, antibody Tyr1604 has been utilized frequently to detect p-ALK in multiple malignancies including HCC, non-small cell lung carcinoma as well as neuroblastoma." (PMID 34029351, 2021). "The treatment of anaplastic lymphoma kinase (ALK)-positive locally advanced non-small-cell lung cancer (NSCLC) is challenging because there is no randomized controlled trial has been reported." (PMID 33816312, 2021). "Whereas there are many pharmacological interventions prescribed for patients with advanced anaplastic lymphoma kinase (ALK)- rearranged non-small cell lung cancer (NSCLC), comparative data between novel generation ALK-tyrosine kinase inhibitors (TKIs) remain scant." (PMID 34836510, 2021). "Other frequently recurring fused kinases are ALK (found in 18 cell lines) and ROS1 (in 6 cell lines), both well known as cancer drivers in lung adenocarcinoma (EML4-ALK fusion) and non-small cell lung cancer (ROS1 rearrangements), for which different inhibitor drugs have been developed." (PMID 33257674, 2020). "During this study, we screened 187 ALK-positive metastatic NSCLC patients and identified 27 patients with SBM, the synchronous brain metastasis frequency of patients with in ALK-rearranged non-small cell lung cancer is 14.4%." (PMID 31777594, 2019). "Activation of ALK/STAT3 in T cell lymphoma, AP-1/JAK/STAT in classical Hodgkin lymphoma (cHL), the microRNA-200/ZEB1 axis in non-small-cell lung cancer (NSCLC), c-jun/STAT3 in BRAF inhibitor-resistant melanoma, and PI3K in glioma have each been reported to upregulate PD-L1 expression on tumor cells." (PMID 31730010, 2019).
non-small cell lung carcinoma (continued). "ALK is a receptor protein-tyrosine kinase and its aberration is observed in several human malignancies, such as ALCL, neuroblastoma, inflammatory myofibroblastic tumor, or non-small cell lung carcinoma (NSCLC)." (PMID 29510549, 2018). "Non-small-cell lung cancer (NSCLC) was the second non-hematological tumor in which oncogenic ALK fusion were detected." (PMID 29495603, 2018). "Multitargeted small molecule tyrosine kinase inhibitors of dual ALK and c-MET inhibition have been studied and FDA approved in non-small cell lung cancer and c-MET inhibition may be a potential therapeutic target in human lymphomas." (PMID 29854308, 2018). "Non-Small-Cell Lung Cancer (NSCLC) is a poorly chemosensitive tumor and targeted therapies are only used for about 15% of patients where a specific driving and druggable lesion is observed (EGFR, ALK, ROS)." (PMID 29343688, 2018). "Therefore, ALK fusion proteins are already important clinical targets in non-small cell lung cancer (EMLA4-ALK) but have also been described in diffuse large cell lymphoma (NPM-ALK) and in inflammatory myofibroblastic tumour (TPM3-ALK)." (PMID 30290811, 2018). "For example, ALK overexpressing cell line, PANC-1, showed a striking synergy when ONC212 was added with crizotinib, which is currently approved for ALK expressing locally advanced or metastatic non-small cell lung cancer." (PMID 29137221, 2017). "The purpose of this study was to test genetic biomarkers used in clinical practice (EGFR, ALK) and candidate biomarkers identified by the French National Cancer Institute (KRAS, BRAF, PIK3CA, HER2) in patients with metastatic non-small-cell lung cancer for whom two tumor samples were available." (PMID 26968843, 2016). "ALK rearrangement was identified in 13 patients (1.7 %), including nine adenocarcinomas, two non-small cell carcinoma not otherwise specified (NOS), and two squamous cell carcinomas." (PMID 27495736, 2016). "In order to assess the utility of this system for analysis of targeted therapies, we subjected two established non-small cell lung cancer cell lines H522 and H3122 to crizotinib treatment, a tyrosine kinase inhibitor (TKI) with activity against ALK, ROS1 and CMET." (PMID 27548442, 2016). "The aberrant activity of ALK fusions, as a consequence of chromosomal rearrangements, leads to the development of multiple malignancies such as non-small cell lung cancer (NSCLC) and ALK-positive ALCL (the latter representing ∼ 50–80% of all ALCLs of which in ∼ 85% ALK is fused with NPM)." (PMID 27669408, 2016). "Notably, the combination of OTX015 with crizotinib, one of several ALKi FDA-approved agents for the treatment of ALK+ non-small cell lung cancer, or with CEP28122, a selective ALKi, were found to be highly effective in our ALK+ ALCL cell lines." (PMID 27793034, 2016). "Similarly, in mesenchymal non-small-cell lung cancer cell lines with EMT features, resistance to erlotinib and upregulation of AXL was associated with markedly increased levels of GAS6.16, 17 Therefore, cleaved soluble GAS6 could be exploited as a biomarker of resistance to ALK inhibition." (PMID 26616860, 2016). "The discovery of anaplastic lymphoma kinase (ALK) rearrangement in non-small cell lung cancer (NSCLC) in 2007 and the approval of crizotinib for the treatment of advanced ALK-rearranged NSCLC in 2011 represents a landmark in the development of targeted oncology therapy." (PMID 24744988, 2014). "In non-small cell lung carcinoma (NSCLC), the most common ALK rearrangement is a fusion of ALK gene and echinoderm microtubule-associated protein-like 4 (EML4) gene, formed as a result of a small inversion within the short arm of chromosome 2, where the genes are located." (PMID 23484153, 2013). "Mutations in SMARCA4 have been shown to co-exist with KRAS mutations but are mutually exclusive from common targetable non-small cell lung carcinoma (NSCLC) oncogenes, including EGFR, ALK, MET, ROS-1, and RET." (PMID 40406754, 2025).